STEAP3 (STEAP3 metalloreductase)
Diseases named in the same sentence as STEAP3 in open-access papers (continued):
Sharing a sentence is not in itself a finding about the gene and the disease.
Sepsis (1 paper, 2023). Sepsis is defined as life-threatening organ dysfunction caused by a dysregulated host response to infection. "This study identified two FR-DEGs (Ncf2 and Steap3) associated with sepsis-induced ALI via transcriptome analyses, as well as their functional and metabolic pathways." (PMID 37081490, 2023). "Eventually, the genes chosen by the two models were combined to further screen diagnostic genes for sepsis-induced ALI, and three common genes (Ncf2, Steap3, and Gclc) were obtained." (PMID 37081490, 2023). "Sepsis is a disease characterized by inflammatory dysfunction, and some GO terms of inflammation, including leukocyte differentiation and bacterial responses, were identified in relation to Ncf2 and Steap3." (PMID 37081490, 2023). "Nevertheless, whether Steap3 regulates sepsis-induced ALI through the ferroptosis pathway remains unclear." (PMID 37081490, 2023). "Our results showed that some inflammatory signal-relevant pathways were enriched by Ncf2 and Steap3, such as the JAK-STAT, MAPK, and cytokine activation signaling pathways, which have been shown to be involved in ferroptosis and sepsis-induced lung injury." (PMID 37081490, 2023). "In general, in the process of sepsis-induced ALI, Ncf2 and Steap3 mainly participate in disease pathways involved in infection, immunity, and inflammation." (PMID 37081490, 2023). "Validation results using GSE165226 showed that the expression of Ncf2 was significantly higher in sepsis-induced ALI samples, whereas the expression of Steap3 was higher in the control samples." (PMID 37081490, 2023). "The boxplot revealed 26 differentially expressed genes between the sepsis-induced ALI and control samples: Ncf2, Slc2a6, Cd44, Txnip, Slc2a1, Ubc, Hspb1, Zfp36, Arntl, Ddit4, Tnfaip3, Txnrd1, Mt1, Hmox1, Gch1, Gclc, Stat3, Egfr, Hif1a, Bach1, Socs1, Dusp1, Cdkn1a, Fth1, Steap3, and Alox12." (PMID 37081490, 2023). "Moreover, the differential expression of Ncf2 and Steap3 were verified in GSE165226, GSE168796 and qRT-PCR, which may provide a reference for the pathogenesis of sepsis-induced ALI from the perspective of bioinformatics." (PMID 37081490, 2023).
squamous cell carcinoma (1 paper, 2023). A carcinoma arising from squamous epithelial cells. "In addition, in previous bioinformatics analyses of hepatocellular, basal cell (BCC), and squamous cell carcinomas, Steap3 was identified as a novel diagnostic and prognostic gene associated with ferroptosis." (PMID 37081490, 2023).
tumor (37 papers, 2010 to 2025). "Meanwhile, the up-regulated expression of genes, including Maob, Sord, Steap3 and Gpx8 are associated with oxidative stress, illustrating that the produced ROS plays an important role in tumor growth inhibition." (PMID 36435848, 2022). "High STEAP3 expression is associated with gender, hemoglobin level, pathological grade, tumor stage and significantly predicts an unfavorable prognosis of ccRCC patients." (PMID 36424540, 2022). "The expression level of STEAP3 was positively correlated with the markers of multiple immune-suppressive cells including Treg, T exhausted cell, monocyte, macrophage, tumor-associated macrophage (TAM), MDSC and tumor-associated fibroblasts (CAF)." (PMID 36424540, 2022). "We further explored the association between STEAP3 expression and gene markers of these tumor-infiltrating immune cells (NK, Th17, neutrophils and Tfh) by immunohistochemical images in LIHC tissues." (PMID 34790664, 2021). "The other risk factors LOXL1, LOXL2, and STEAP3 were highly expressed in almost all tumor zones (CT, HBVs, MVP, PAN, PNZ, IT) and showed the lowest expression in the peritumor zone (LE), while the protective factor F5 showed no obvious change between the tumor and peritumor zone." (PMID 37891828, 2023). "Interestingly, STEAP3 overexpression in gliomas is associated with increased cell proliferation and tumor-growth phenotype." (PMID 36011027, 2022). "The findings indicated that SERPING1 and STEAP3 were aberrantly regulated in the majority of tumours." (PMID 39853609, 2025). "We conducted a more in‐depth examination of the functions of SERPING1 and STEAP3 inside the tumour microenvironment of HCC." (PMID 39853609, 2025). "For OC, we performed further analysis and found that the expression level of STEAP3 in tumor tissues was significantly higher than that in normal tissues." (PMID 38440354, 2024). "To further confirm the effect of STEAP3 in OC cells in vivo, we established subcutaneous tumor models carrying normal SKOV3 cells and STEAP3 knockdown SKOV3 cells, respectively." (PMID 38440354, 2024). "What's more, we obtained tissue samples from OC patients from the clinic and detected the expression levels of STEAP3 in tumor tissues and paracancerous tissues." (PMID 38440354, 2024). "STEAP3 is a new prognostic biomarker for ccRCC and exerts tumor‐promoting function via stimulating the invasion and EMT and inducing recruitment and polarization of M2 macrophages." (PMID 37344930, 2023). "In ccRCC, STEAP3 was expressed at high levels in tumor tissues suggesting poor prognosis and correlated significantly with both clinical stages and pathological grades." (PMID 37344930, 2023). "To gain more insights into STEAP3's expression profile, we evaluated its mRNA expression in 946 tumor cell lines from the CCLE database." (PMID 37344930, 2023). "STEAP3 mRNA levels were elevated in the ccRCC tumor tissues relative to the normal tissues according to the TCGA and GSE15641 databases." (PMID 37344930, 2023). "Our findings revealed significant correlations between AURKA, CDKN1A, and STEAP3 and tumor exclusion." (PMID 37608887, 2023). "Particularly in KIRC, there was an upward trend in STEAP3 expression with increasing tumor stage and pathological grade." (PMID 37344930, 2023). "Then we evaluated immunohistochemical (IHC) staining of STEAP3 proteins in tumor samples and normal tissues using the HPA database." (PMID 37009153, 2023). "STEAP3 is a novel biological marker for determining prognosis, and it also performs a remarkable function in the promotion of tumor growth in ccRCC by enhancing invasion and EMT, as well as by triggering the recruitment and polarization of M2 macrophages." (PMID 37344930, 2023). "It has been proven that STEAP3 overexpression is involved in tumor progression and predicts poor outcomes in several types of cancer." (PMID 37386521, 2023).
tumor (continued). "Precisely, reducing matrix stiffness in HCC leads to STEAP3 downregulation and attenuation of ferroptosis that can enhance the anti-tumor effect mediated by PD-L2." (PMID 38131014, 2023). "And STEAP3 expression in TNBC was significantly higher than non-TNBC.These findings show that, compared to relevant control samples, TNBC tumor cells and tissue exhibit a considerable up-regulation of STEAP3 at the mRNA and protein levels." (PMID 37064114, 2023). "We used the TIMER2.0 database to explore the differential expression of STEAP3 between tumor samples and adjacent normal tissues." (PMID 37009153, 2023). "Here, we identified that matrix stiffness suppressed ferroptosis of HCC cells through regulating the expression of STEAP3, which in turn shaped matrix mechanic-driven tumor immunity environment in HCC partly via PD-L2." (PMID 36229881, 2022). "An approximately downward trend with STEAP3 in different tumor stages (TS) and tumor grades (TG) of HCC patients were observed, respectively." (PMID 36229881, 2022). "Collectively, these findings demonstrated that matrix mechanics mediated the ferroptosis of HCC cells and tumor immune environments through STEAP3 and PD-L2." (PMID 36229881, 2022). "Taken together, these results demonstrated that STEAP3 directed immune microenvironment through immune infiltration in cirrhotic HCC, indicating its association with tumor immunity." (PMID 36229881, 2022). "For example, data suggest that STEAP3 is a relatively ubiquitous tumor suppressor that induces apoptosis via a caspase-3-dependent pathway." (PMID 36011027, 2022). "The data from the CPTAC database showed that the protein expression level of STEAP3 was also significantly higher in tumor tissues." (PMID 36424540, 2022). "The functional enrichment analysis showed that compared with STEAP3 low-expression ccRCC, STEAP3 high-expression ccRCC had obvious degradation and remodeling of tumor extracellular matrix." (PMID 36424540, 2022). "As for ccRCC, the mRNA and protein expression levels of STEAP3 were significantly up-regulated in tumor tissues, and STEAP3 expression was negatively correlated with the prognosis of ccRCC." (PMID 36424540, 2022). "Our findings identify that STEAP3 characterize matrix mechanical heterogeneity and immune environment of tumor, and possess prognosis and predictive value of clinical outcome in cirrhotic HCC." (PMID 36229881, 2022). "In ccRCC, we found that the mRNA expression level of STEAP3 in tumor tissues was higher compared with normal tissues, and paired comparison also indicated that the mRNA expression in tumor tissues was significantly higher than in adjacent tissues." (PMID 36424540, 2022). "Consistent with previous studies, our results showed that the gene feature (expression level and copy number) of STEAP3 was closely correlated with the numbers of tumor-infiltrated immune cells (e.g., CD8+ T cells) in HCC." (PMID 36229881, 2022). "By integrating information from multiple public databases, we found that STEAP3 was abnormally expressed in various tumor tissues, and its expression was significantly correlated with the prognosis of cancer patients." (PMID 36424540, 2022). "SERPING1 and STEAP3 affect tumour cells and modify the tumour microenvironment (TME), indicating that targeting these genes may offer a viable immunotherapeutic approach for HCC in clinical settings." (PMID 39853609, 2025). "In general, the expression of STEAP3 was elevated in the majority of 32 TCGA tumor types." (PMID 37009153, 2023).
tumor (continued). "Further research revealed that STEAP3 may affect tumor immune response by increasing the infiltration level of M2 macrophages." (PMID 37009153, 2023). "Finally, the functional role of STEAP3 in tumor immunity requires in-depth experimental verification." (PMID 37386521, 2023). "The reduction of STEAP3 impairs ferroptosis of tumor cells and promotes HCC progression." (PMID 36229881, 2022). "Furthermore, high STEAP3 expression seemed to regulate the tumor microenvironment of ccRCC through an oxidative stress-dependent manner." (PMID 36424540, 2022). "Generally, these results suggested STEAP3 could affect tumor immune microenvironment via regulating matrix stiffness-dependent immune checkpoint receptor PD-L2 in HCC cells." (PMID 36229881, 2022). "However, there are also data that show that STEAP3 promotes iron storage and tumor proliferation in Raji, a Burkitt lymphoma B-cell line, when iron levels are low." (PMID 36011027, 2022). "However, the mRNA level of STEAP3 was negatively correlated with tumor purity and the infiltration of CD8+ T cell, macrophage and dendritic cell, but positively correlated with CD4+ T cell and neutrophil." (PMID 36229881, 2022). "Functional enrichment analysis and evaluation of the tumor microenvironment indicated that STEAP3 was involved in the remodeling of tumor extracellular matrix and the shaping of an immune-suppressive tumor microenvironment to promote tumor metastasis and evade immune killing." (PMID 36424540, 2022). "This suggested that high STEAP3 expression in ccRCC may contribute to the polarization of macrophages to the anti-inflammatory M2-macrophages, thereby promoting tumor progression." (PMID 36424540, 2022). "Functional enrichment analysis revealed that STEAP3 may promote the growth, invasion, and metastasis of ccRCC by regulating the tumor microenvironment." (PMID 36424540, 2022). "In addition, we analyzed the relationship between STEAP3 and tumor-infiltrating immune cells (TIICs) in LIHC." (PMID 34790664, 2021). "Taken together, STEAP3 may be involved in tumor metastasis in ccRCC." (PMID 37344930, 2023). "Additionally, these co-expressed genes were mainly involved in the regulation of metabolic microenvironment, which hinted that the metabolic regulation of tumor cells may be either direct or indirect through STEAP3 expression." (PMID 34790664, 2021). "It is important to note that a particular subclone with the set of gene mutations (e.g. STEAP3, SLURP1 and KDM6A) within the primary tumor may have grown out or outcompeted the others and survived both chemotherapy selection and allo-HSCT treatment to evolve into the dominant clone at relapse." (PMID 26527318, 2016). "And as expected, STEAP3 and LOXL1 were significantly increased in the tumor core compared to the normal brain area." (PMID 37891828, 2023). "In the Gene Expression database of Normal and Tumor tissues (GENT2) database, STEAP3 mRNA expression was remarkably elevated in most malignancies compared to matched normal tissues containing OC." (PMID 37386521, 2023). "Therefore, we hypothesized that in STEAP3 high-expression ccRCC, the redox reaction involving Fe2 + produced a large number of ROS, and these ROS can promote the process of ccRCC by regulating the tumor microenvironment." (PMID 36424540, 2022). "Particularly, matrix stiffness impairs ferroptosis by downregulating STEAP3 in cirrhotic HCC, which in turn direct the infiltration of tumor immune cells, and exacerbate anti-tumor immunity partly via PD-L2." (PMID 36229881, 2022). "And two FRGs, STEAP3 and HMOX1, formed a synergistic effect on the occurrence of ferroptosis in tumor cells." (PMID 35501667, 2022).
tumor (continued). "Six genes (DNAJB6, RB1, VIMP/SELENOS, STEAP3, BACH1, and ALOX12) had a consistent mRNA expression level in tumor samples and prognosis in the univariate Cox analysis." (PMID 34075060, 2021). "In the HPA database, NRAS, STEAP3, and ALOX5 proteins are significantly expressed in tumor tissues, but the difference in the expression of ZFP36 and GABARAPL1 proteins is not obvious." (PMID 34868262, 2021). "Interestingly, results indicate that SAS treatment increased transferrin and STEAP-3 expression, while decreased ferritin, SLC7A11, and GPx-4 expression, which are the major drivers that protect the tumor cells from ferroptosis." (PMID 39513121, 2024). "The results showed that the knockdown of key genes (HMOX1, STEAP3, and LTF) combined with TMZ treatment significantly decreased both tumor volume and tumor weight compared to the group treated with TMZ alone, indicating an effective restoration of sensitivity to TMZ therapy." (PMID 37545464, 2024). "As for ccRCC, we demonstrated that the expression levels of STEAP3 in tumor tissues were significantly higher compared with normal tissues, and its expression level was negatively correlated with the prognosis of ccRCC." (PMID 36424540, 2022). "From three independent LIHC studies of the GEO database, in comparison with non-cancerous tissues, the expression of STEAP3 was dramatically downregulated in tumor groups (p < 0.001)." (PMID 34790664, 2021). "STEAP family members in different cancers are irregularly expressed and participate in the proliferation, migration, invasion, apoptosis, and prognosis of cancer cells, although STEAP3 and STEAP4 may have tumor suppressor functions in cancers." (PMID 34778263, 2021).